PRSS57 (serine protease 57)
Description:
Serine protease that cleaves preferentially after Arg residues. Can also cleave after citrulline (deimidated arginine) and methylarginine residues.
Synonyms: NSP4; PRSSL1; UNQ782
Tractability: Small molecule: a structure with a bound ligand is known. Antibody: UniProt places it where antibodies can reach, with high confidence; UniProt predicts a signal peptide or a membrane-spanning region; its Gene Ontology location is reachable by antibodies, with medium confidence.
Gene: Protein-coding gene on chromosome 19 (685,546 to 695,498, reverse strand). Ensembl gene ENSG00000185198.
Subcellular location: Cytoplasmic granule lumen; Secreted
Gene Ontology:
Molecular function: heparin binding; serine-type peptidase activity; serine-type endopeptidase activity
Biological process: proteolysis; protein maturation
Cellular component: azurophil granule lumen; extracellular region
Genetic constraint (gnomAD): Loss-of-function variants: 17 observed, 15.76 expected, observed/expected ratio (o/e) 1.08, 90% interval 0.74 to 1.61. The synonymous counts are far from expectation, so gnomAD's model fits this gene poorly and the ratio says little. Missense variants: 421 observed, 306.26 expected, observed/expected ratio (o/e) 1.37, 90% interval 1.27 to 1.49. Synonymous variants: 193 observed, 136.49 expected, observed/expected ratio (o/e) 1.41, 90% interval 1.26 to 1.59.
Homologues: Orthologues: chimpanzee PRSS57 (98% identical), dog PRSS57 (76% identical), pig PRSS57 (72% identical), rat Prss57 (70% identical), mouse Prss57 (69% identical). Paralogues in human: GZMM (37% identical), KLK15 (30% identical), PLG (29% identical), KLK9 (28% identical), PRSS33 (28% identical), PLAT (27% identical), PRSS50 (27% identical), OVCH1 (27% identical), TMPRSS12 (26% identical), PRSS27 (24% identical), PRSS48 (24% identical), PRSS37 (19% identical), and 2 more.
Diseases named in the same sentence as PRSS57 in open-access papers:
PRSS57 is named in the same sentence as 27 diseases in open-access papers, as found by Europe PMC text mining. Sharing a sentence is not in itself a finding about the gene and the disease. The quoted sentences say what the papers report.
leukemia (1 paper, 2022). A malignant (clonal) hematologic disorder, involving hematopoietic stem cells and characterized by the presence of primitive or atypical myeloid or lymphoid cells in the bone marrow and the blood. "AML-GMP expressed granulocyte–monocyte progenitor markers such as Mpo, Elane, Prss57 and Ctsg22,26,33, along with Gstm1, which has been associated with quiescent, therapy-resistant, leukemia-initiating cells in AML35–37." (PMID 36424441, 2022).
ovarian carcinoma (1 paper, 2024). A malignant neoplasm originating from the surface ovarian epithelium. "By targeting many genes, including PRSS57, miR-134-3p can stimulate and inhibit ovarian cancer cell growth." (PMID 39857255, 2024).
PRSS57 also shares sentences with these, for which no sentence is quoted: infection (66 papers); Rotavirus infection (21); viral infection (18); tumor (6); COVID-19 (5); autoimmune disease (2); Co-infection (2); diarrhoea (2); gastroenteritis (2); anaphylaxis (1); asthma (1); biliary atresia (1); carcinoid (1); dengue (1); eastern equine encephalitis (1); gastric cancer (1); gastrointestinal disease (1); Hepatitis B (1); imbalance (1); immune disorders (1); lymphoma (1); neuroblastoma (1); SARS-CoV infection (1); viral diseases (1); western equine encephalitis (1).